TZMP1 (transition zone microprotein 1)
Description:
Required for ciliogenesis.
Synonyms: C9orf133; SMIM27; TOPORS-AS1
Gene: Protein-coding gene on chromosome 9 (32,551,144 to 32,568,621, forward strand). Ensembl gene ENSG00000235453.
Subcellular location: Cell projection, cilium membrane
Gene Ontology:
Biological process: cilium assembly
Cellular component: ciliary transition zone; ciliary membrane
Genetic constraint (gnomAD): Loss-of-function variants: 2 observed, 0.94 expected, observed/expected ratio (o/e) 2.13. That is too few expected variants to judge how well the gene tolerates losing a copy. Missense variants: 28 observed, 16.2 expected, observed/expected ratio (o/e) 1.73, 90% interval 1.24 to 1.96. Synonymous variants: 10 observed, 6.68 expected, observed/expected ratio (o/e) 1.5, 90% interval 0.88 to 1.93.
Homologues: Orthologues: macaque SMIM27 (96% identical), pig SMIM27 (76% identical), dog SMIM27 (75% identical), guinea pig SMIM27 (75% identical), rabbit SMIM27 (71% identical).
Diseases named in the same sentence as TZMP1 in open-access papers:
TZMP1 is named in the same sentence as 2 diseases in open-access papers, as found by Europe PMC text mining. Sharing a sentence is not in itself a finding about the gene and the disease.
TZMP1 shares sentences with these, for which no sentence is quoted: breast carcinoma (1 paper); ovarian carcinoma (1).